C5 (complement C5)
Diseases named in the same sentence as C5 in open-access papers (continued):
Sharing a sentence is not in itself a finding about the gene and the disease.
Obesity (7 papers, 2017 to 2025). Accumulation of substantial excess body fat. "Anti-C5 treatment in these mice did not have any effect on the development of obesity or associated metabolic risk factors and did not affect the development of steatosis, inflammation or fibrosis in the liver." (PMID 36142647, 2022). "Tumor tissues from HFD-IF mice diminished C5, IL-1β, CCL3, and CXCL2 protein levels compared to those from HFD mice, indicating that IF attenuates obesity-induced inflammatory conditions in the tumor microenvironment." (PMID 38999849, 2024). "In the heavier co-twins, upregulation of complement inhibitors and downregulation of the expression of C5 and C6 indicate that excessive early pathway activation in obesity does not translate into the terminal pathway." (PMID 28559893, 2017). "In our study, in a context of obesity (i.e., chronic low-grade inflammation), the blood-brain barrier is likely to be less permeable and the systemic anti-C5 treatment may not have entered the brain to target local production of complement factors." (PMID 37457817, 2023).
breast cancer (6 papers, 2017 to 2023). A primary or metastatic malignant neoplasm involving the breast. "For example, activation of the complement components C5 and C5a in cancer tissues and expression of C5aR1 in breast cancer cells is linked to a poor prognosis." (PMID 36508191, 2023). "Indeed, in mouse models, C5 deficiency drastically decreases the hepatic metastasis in colorectal cancer and C5aR facilitates the lung metastasis in breast cancer." (PMID 33113844, 2020).
colorectal cancer (6 papers, 2019 to 2025). A primary or metastatic malignant neoplasm that affects the colon or rectum. "Interestingly, C5 mRNA levels were also increased following treatment with UPR inducers in colorectal cancer HCT116 cells." (PMID 40695778, 2025).
complement deficiency (6 papers, 2019 to 2025). A genetic deficiency of any of the component of the complement system (including the classical, alternative, and terminal pathway components), that can either be acquired or inherited. "The important role of complement activation in CIA pathology is supported by studies that demonstrated amelioration of CIA in response to complement deficiency and that C5-deficient mice were resistant to CIA development." (PMID 33805383, 2021). "Therapeutic anti-C5 monoclonal antibodies (e.g. Eculizumab) are used in a variety of conditions such as atypical haemolytic uraemic syndrome and paroxysmal nocturnal haemoglobinuria and by design induce an acquired terminal pathway complement deficiency." (PMID 40916471, 2025). "In addition to the primary complement deficiencies, we identified two groups with acquired complement deficiency, those with immune disorders leading to secondary complement deficiency and iatrogenic cases in patients receiving Eculizumab, a humanised monoclonal complement C5 inhibitor." (PMID 31200658, 2019). "Laboratory investigations revealed a marked absence of C5 protein and a severely reduced CH50 activity, consistent with a complement deficiency." (PMID 40692790, 2025).
fungal infections (6 papers, 2022 to 2025). "The C5-deficiency results in the loss of the activation of the complement cascade and delayed neutrophil recruitment to the site of infection leaving these mice susceptible to a myriad of bacterial and fungal infections (22, –, 25)." (PMID 38010145, 2023). "The genetic target C5-deficiency (Hc0 allele, hemolytic complement) modulates the host’s initial response and causes susceptibility and ineffective inflammatory response against fungal infections." (PMID 36520787, 2022). "Furthermore, a hereditary deficiency of C5 or treatment with the US Food and Drug Administration–approved anti-C5 monoclonal antibody (eculizumab) often leads to severe, life-threatening fungal infections, highlighting the complement system’s essential role in tackling fungal pathogens." (PMID 39854185, 2025). "For instance, reduced serum C5a levels or suboptimal complement activation due to C5 single nucleotide polymorphisms are independent risk factors for poor outcomes in patients with candidemia, this helps explain the susceptibility of patients treated with avacopan to fungal infections." (PMID 41131744, 2025). "Interestingly, a similar differential susceptibility to fungal infection between acute pharmacological inhibition of an immunological pathway and inherited deficiency of the same pathway has also been observed with C5-targeted monoclonal antibody therapy and inherited C5 deficiency." (PMID 38696257, 2024). "The complement system plays a crucial role in bacterial and fungal infections, with complement activation ultimately resulting in the cleavage of C5 into C5a and C5b." (PMID 41131744, 2025). "In the context of fungal infection, complement C5 has been identified as the dominant gene responsible for altering the susceptibility to systemic Candida infection." (PMID 36211424, 2022).
HELLP syndrome (6 papers, 2021 to 2025). A life-threatening condition that can potentially complicate pregnancy. "Since the involvement of complement has been reported in multiple studies, C5 monoclonal antibody eculizumab has been tested to treat HELLP syndrome." (PMID 40746214, 2025). "Furthermore, a clinical trial with eculizumab, a long-acting human monoclonal antibody targeting C5 to block its cleavage to C5a and C5b, has shown positive results in phase 1 clinical trials of pregnant women with early-onset HELLP syndrome." (PMID 40904461, 2025). "Around the same time, Burwick and Feinberg were the first to show that C5 blockade with eculizumab could also be used effectively to treat preeclampsia and HELLP syndrome, consistent with the protective effects seen with soluble CR1 and C5a antagonism in animal models." (PMID 40777009, 2025). "Moreover, Burwick and colleagues successfully treated patients with HELLP syndrome with eculizumab (a C5 targeted inhibitor), which showed that suppressing complement activation could improve HDP symptoms." (PMID 33874952, 2021).
IgA nephropathy (6 papers, 2016 to 2024). "The first long-acting complement inhibitor, ravulizumab, has similar effects by C5 antagonism and is currently under preclinical evaluation in IgA nephropathy." (PMID 38069385, 2023). "Recent case reports on the successful use of humanized anti-C5 monoclonal antibody eculizumab are consistent with this hypothesis, but a better understanding of the role of complement in IgA nephropathy is needed to guide future therapeutic interventions." (PMID 30941137, 2019).
kidney damage (6 papers, 2019 to 2026). "Discontinuation of C5 inhibitor for selected patients is safe and has been confirmed in many observations; however, patients with a known high risk of relapse are also at risk for irreversible kidney damage in the future." (PMID 39549043, 2025). "Six and twenty weeks after AAV8-FHR51-9FH1-5 treatment in hFH-FHR5mut mice (a mouse model of CFHR5 nephropathy) glomerular C3b/iC3b/C3c, C3d, and C5 were significantly reduced and properdin resolved completely compared to controls." (PMID 41810513, 2026). "Pre-administration of AAV-FHR51-9FH1-5 also ameliorated abnormal glomerular C3b/iC3b/C3c, C3d, C5, and properdin in a triggered CFHR5 nephropathy model." (PMID 41810513, 2026). "Therefore, the use of the anti-C5 antibody does not completely reverse the kidney damage." (PMID 31662004, 2019).
liver fibrosis (6 papers, 2019 to 2023). "C5 or C5aR1 deficiency diminished hepatic fibrosis, inflammatory response, and lipid accumulation in NASH." (PMID 37227481, 2023). "We found that compared to the WT mice, C5 deficiency resulted in a reduction of liver fibrosis in the NASH model." (PMID 37227481, 2023). "We speculate that C5 deficiency attenuates liver fibrosis through the anaphylatoxin receptor C5aR1 in NASH mice." (PMID 37227481, 2023). "A single nucleotide polymorphism affecting C5 (rs17611), which was previously linked to elevated C5 in serum and susceptibility to the complement-associated disease liver fibrosis, was shown to be more prevalent in patients with periodontitis than in healthy controls." (PMID 30915073, 2019). "Serum hyaluronic acid, a well-known parameter of liver fibrosis, was significantly lower in Group-PS+Anti-C5 than in Group-PS (P =0.02)." (PMID 37398677, 2023). "Complement C5 was identified as a critical factor for liver fibrosis in mice and humans." (PMID 37227481, 2023). "In addition, the pro-fibrotic role of C5 have been observed also in renal and liver fibrosis." (PMID 34424905, 2021). "Notably, just two doses of Anti-C5 only on PTD-0 and -3 significantly improved biliary injury and liver fibrosis up to PTD-100, leading to better long-term animal survival (P =0.02)." (PMID 37398677, 2023).
melanoma (6 papers, 2003 to 2022). A malignant, usually aggressive tumor composed of atypical, neoplastic melanocytes. "C5, which encodes a component of the complement system and has previously been shown to be significantly differentially expressed in anti-PD-1 treatment-resistant and -sensitive melanoma patients, was upregulated in PR patient." (PMID 36171464, 2022). "C1q-deficient (C1qa−/−) mice, bearing a syngeneic B16 melanoma, exhibited slower tumor growth and prolonged survival, compared to C3 or C5 deficient mice although it has been shown that C3/C5 deficiency may also create microenvironment suboptimal for tumor growth." (PMID 31130944, 2019). "In contrast, high C5 expression was associated with a worse outcome of ICB therapy of PD1, CTLA4, and ACT in melanoma but predicted a good outcome of PD1 therapy in GBM and kidney cancer." (PMID 34439277, 2021). "The pattern is consistent with (but more complex than) other studies using melanoma cells and the C5 antibody or another antibody (D5) in which an ∼55–60 kDa Mitf-M doublet is detected." (PMID 12966428, 2003). "Therefore, we investigated the expression of complement components C1R, C1S, C5, and C3 by qRT-PCR in MCs treated with melanoma cell-derived conditioned medium." (PMID 35669782, 2022). "In conclusion, the complement components C3, C5, C3AR1, and C5AR1 demonstrated a context-dependent association with tumor immune evasion, prognosis, and therapy response with high implicative value in melanoma, colorectal, brain, breast, stomach, and renal cancer." (PMID 34439277, 2021). "We used immunohistochemistry (IHC) staining and analyzed the expression of these putative biomarkers (complement component 3 (C3), complement component 5 (C5), and absent in melanoma 2 (AIM2)) based on the staining area and intensity of the color reaction to predict BEV efficacy in EOC patients." (PMID 34640548, 2021).
Alzheimer disease (5 papers, 2011 to 2022). A progressive, neurodegenerative disease characterized by loss of function and death of nerve cells in several areas of the brain leading to loss of cognitive function such as memory and language. "In Alzheimer’s disease, antibody-mediated suppression of C1q has been shown to ameliorate synapse removal in TauP301S transgenic mice, while C5 inhibitors are currently being trialled for ALS (ID: NCT0424845)." (PMID 35148379, 2022).
lung carcinoma (5 papers, 2019 to 2024). "Specifically, upregulated complement factors were also found in the MPE, and C5 was associated with poor overall survival in the lung cancer patients with epidermal growth factor receptor mutation." (PMID 37649596, 2023). "In lung cancer cell lines, incubation with normal human serum has been demonstrated to activate complement and give rise to increased C5 deposits when compared to cell lines derived from the normal bronchial epithelium." (PMID 33802004, 2021).
malaria (5 papers, 2008 to 2022). Malaria is a serious and sometimes fatal disease caused by a parasite that commonly infects a certain type of mosquito which feeds on humans. "To further characterize the role of complement in the pathogenesis of malaria and SMA, we explored two novel missense mutations in the C5 gene and its association with malaria, SMA and all-cause mortality." (PMID 36186473, 2022). "It was observed that the levels of Complement C3 and Complement C4-B, Complement C5, Complement C9, Complement factor B and Complement C1q subcomponent subunit C were significantly elevated in malaria plasma MPs compared to controls." (PMID 28352210, 2016). "In the present study, the dynamics of complement factors C1q, C3 and C5 in the brains and sera of mice with malaria were investigated." (PMID 18847493, 2008). "Though there is some evidence for a role of the inflammatory complement C5a protein in disease, the anti-C5 monoclonal antibody eculizumab has not been studied in malaria." (PMID 34168652, 2021).
meningitis (5 papers, 2015 to 2025). A disorder characterized by acute inflammation of the meninges of the brain and/or spinal cord. "Complement C5 deficiency is a rare primary immunodeficiency strongly associated with recurrent bacterial infections, particularly meningitis caused by Neisseria spp." (PMID 40692790, 2025). "Adjunctive treatment with dexamethasone plus anti-C5 antibodies improves survival in severe experimental meningitis caused by S. pneumoniae serotype 3, posing an important new treatment strategy for patients with pneumococcal meningitis." (PMID 26272468, 2015).
ovarian carcinoma (5 papers, 2015 to 2022). A malignant neoplasm originating from the surface ovarian epithelium. "LncOVM interacts with and stabilizes PPIP5K2 by suppressing ubiquitinated degradation to promote complement C5 secretion from ovarian cancer cells." (PMID 35813475, 2022). "For instance, LncRNA OVM interacts with and stabilizes PPIP5K2 by reducing its ubiquitinated degradation, allowing ovarian cancer cells to secrete complement C5." (PMID 36471363, 2022). "Some studies have used the syngeneic intraperitoneal injection of ID-8-MOSEC, a mouse epithelial ovarian cancer cell line originating in C57BL/6 mice, to evaluate the roles of C3, C5, and C5aR1 in ovarian cancer development and progression." (PMID 34359708, 2021). "Recently, an autocrine effect of complement proteins has been shown; specifically, C3 and C5 are secreted by ovarian cancer cells on tumor growth." (PMID 26540631, 2015). "Suppressing MSDC infiltration could serve as an option for treating ovarian cancer patients through disrupting the signaling of LncOVM-PPIP5K2-complement axis with C5aR inhibitor or C5 antibodies." (PMID 35813475, 2022). "Moreover, we demonstrated that complement C5 was a big player in recruiting MDSCs into TME, leading to ovarian cancer progression." (PMID 35813475, 2022).
periodontitis (5 papers, 2016 to 2024). An acute or chronic inflammatory process that affects the tissues that surround and support the teeth. "Nevertheless, the availability of C5 genome-wide association studies (GWAS) and the periodontitis GWAS created the opportunity to study the potential therapeutic impact of the genetically proxied inhibition of C5 using cis-IVs on periodontitis risk." (PMID 39439802, 2024). "In this analysis, we selected independent SNPs from the vicinity of the C5 gene locus associated with IL-17 plasma levels, and we observed a reduced risk of periodontitis aligning with our primary findings." (PMID 39439802, 2024). "Recently, this approach has been developed to investigate the relationship between a druggable protein, like C5, and disease risk, like periodontitis." (PMID 39439802, 2024). "In our primary analysis, C5 inhibition was linked to a reduced risk of periodontitis (OR 0.89 [95% CI 0.80, 0.98])." (PMID 39439802, 2024). "The findings from our study suggest that C5 inhibition may reduce the risk of periodontitis, prioritizing C5 inhibitors as a potential adjunctive therapeutic intervention in this disease." (PMID 39439802, 2024). "Our findings suggest prioritizing C5 inhibition as a potential treatment for periodontitis; nevertheless, the efficacy of C5 inhibition in periodontitis is yet to be assessed in preclinical and clinical trials." (PMID 39439802, 2024). "In contrast, complement C1q, FB, Bb, C3, C3a, C3b, C3c, C3d, C4, C5, C5a, C5b and C9 have all been detected in diseased periodontal tissue and in the gingival crevicular fluid from patients with established periodontitis." (PMID 35572583, 2022). "It has been previously hypothesized that inhibiting the activity of complement component C5 by targeting the C5a receptor is a powerful candidate for treating periodontitis." (PMID 39439802, 2024). "However, exploring C5 inhibition to change the risk of periodontitis has not been extensively studied, there is only robust biological plausibility for this hypothesis." (PMID 39439802, 2024).
pneumococcal meningitis (5 papers, 2015 to 2021). An acute purulent infection of the meninges and subarachnoid space caused by Streptococcus pneumoniae, most prevalent in children and adults over the age of 60. "Inhibition of complement component 5 (C5), blocking the common terminal pathway of the complement system was shown to reduce inflammation and improve the outcome of experimental pneumococcal meningitis." (PMID 31883521, 2019). "The protective effect holds promise for future treatment of patients with pneumococcal meningitis, but the effect size seemed to be smaller than previously observed for adjunctive treatment with anti-C5 antibodies." (PMID 28086930, 2017). "We compared adjunctive treatment with placebo, dexamethasone, anti-C5 antibodies, and the combination of dexamethasone plus anti-C5 antibodies in experimental pneumococcal meningitis." (PMID 26272468, 2015). "Neutralization experiments showed that adjunctive treatment with anti-C5 antibodies improved outcome in mice with pneumococcal meningitis." (PMID 26272468, 2015). "We showed that inhibition of complement component C5 improves outcome in serotypes 2 and 3 pneumococcal meningitis, suggesting the effect of anti-C5 antibodies is serotype independent." (PMID 26272468, 2015). "The results of our randomized study show that adjunctive treatment with dexamethasone plus anti-C5 antibodies is beneficial in experimental pneumococcal meningitis." (PMID 26272468, 2015). "However, experiments using adjunctive treatment with anti-C5 antibodies were performed in a model of pneumococcal meningitis with high disease severity, with a mortality rate of 100% in the placebo group." (PMID 28086930, 2017). "Our data provide further evidence for the efficacy of complement inhibition in pneumococcal meningitis, supporting the need for a phase II clinical trial to evaluate the effect of combined adjunctive dexamethasone plus C5-antibody treatment in patients with pneumococcal meningitis." (PMID 26272468, 2015). "Furthermore, anti-C5 antibody treatment was not administered together with dexamethasone, which is currently the standard therapy in pneumococcal meningitis." (PMID 26272468, 2015).
renal failure (5 papers, 2022 to 2025). "The overall treatment experience with the current practice patterns is favourable, with only 12% of patients developing permanent kidney failure despite C5 inhibitor therapy and no increased risk of poor long-term kidney function outcomes in patients in whom treatment is electively discontinued." (PMID 40224677, 2025).